PTGDS (prostaglandin D2 synthase)
Diseases named in the same sentence as PTGDS in open-access papers (continued):
Sharing a sentence is not in itself a finding about the gene and the disease.
tumor (continued). "On the other hand, the activation of evading anti-growth signaling with the down-regulation of prostaglandin D2 synthase was a tumor-accelerated response that continued after 24 h of treatment with TPA." (PMID 35328637, 2022). "The results showed that PTGDS had high expression levels in normal tissues and low expression levels in tumor tissues, while SNX10 showed an opposite profile." (PMID 34116656, 2021). "Lipocalin 2 (LCN2), which belonged to the lipocalin superfamily the same as PTGDS, had been widely studied in various tumours." (PMID 32047563, 2020). "By contrast, SEMA4B, KRT1, KRT9, FBLN1, and PTGDS are involved in the anti-invasive activity of tumor cells." (PMID 32953262, 2020). "Among the overexpressed genes, PTGDS (13.761-fold) had the highest log2 fold change in tumor versus non-tumor tissues, followed by TNFRSF18 (13.387-fold), glial fibrillary acidic protein (GFAP) (12.296-fold), BARHL1 (12.175-fold), and KIF26A (11.719-fold)." (PMID 30195786, 2018). "The inflammatory response-related genes (CCL14 (−4.52), LEP (−3.73) and PTGDS (−3.84)) showed decreased expression in the recurrence tumor tissues." (PMID 24377043, 2013). "The discrepancy of the regulatory role of PTGDS in different tumors might result from the diverse downstream regulatory networks, the high heterogeneity of tumor cells, and the complexity of tumor microenvironment." (PMID 39706989, 2025). "Taken together, above results indicated that targeting PTGDS might promote ferroptosis process and tumor development through regulating iron metabolism in PTCL." (PMID 39706989, 2025). "We also found that the treatment with Fer-1 and DFO could reverse the combined anti-tumor effects of Sorafenib and PTGDS knockdown in PTCL cells, indicating that ferroptosis played important role in the inhibitory effects." (PMID 39706989, 2025). "Additionally, PTGDS was one of the DEGs that was upregulated only in the NR group in the tumor and stromal regions of the eight internal HGSOC samples." (PMID 39135097, 2024). "Additionally, lower PTGDS expression in the tumor and stromal regions was observed in the R group than in the NR group based on our ST data." (PMID 39135097, 2024). "Our findings indicated a significant increase in the expression of PTGDS and PTGIS, which indirectly suggests that the 1-cm area is associated with an increase in prostaglandin metabolites and may be at risk of promoting tumor progression." (PMID 38062443, 2023). "PTGDS expression is correlated with advanced tumor stages, metastasis, and poor prognosis." (PMID 37063972, 2023). "In addition, except for PACSIN1 (P > 0.05), the expression levels of FAM107A (P < 0.05) and PTGDS (P < 0.05) were significantly different between tumour and normal samples." (PMID 37325056, 2023). "We found that the mRNA levels of PTGDS and its receptor prostaglandin D2 receptor (PTGDR) were downregulated in tumours with larger size, higher stage, and higher histological grade, suggesting that PTGDS could serve as a protective factor." (PMID 32047563, 2020). "Compared with mice receiving control treatment, tumor tissue from mice with AT56 treatment and PTGDS knockdown displayed increased level of Fe2+." (PMID 39706989, 2025). "Firstly, relative genes involved in PGD2 signaling axis, HPGDS, PTGDS, PTGDR and SLCO2A1, were all significantly lower expressed in tumor lung tissue compared to normal in TCGA-LUAD cohort." (PMID 40474982, 2025). "The RT-qPCR results showed that PTGDS and PTGDR mRNA levels were lower in tumor tissues than in normal tissues." (PMID 40474982, 2025). "Decreased growth rate, low tumor volume and weight were observed in mice bearing PTCL cells with PTGDS knockdown at the end of experiment." (PMID 39706989, 2025). "Collectively, these findings suggest that both PTGDS and PTGDR are downregulated in LUAD tumor tissues, with their expression patterns further substantiated in corresponding cell types." (PMID 40474982, 2025).
tumor (continued). "To confirm the expression patterns of PTGDS and PTGDR in tumor and normal tissues, we conducted a series of preliminary experiments using five pairs of LUAD tumor and distant normal lung tissues." (PMID 40474982, 2025). "The first cluster exhibits upregulation of CXCL12, PTGDS, KCNN3, suggesting CXCL12-high fibroblasts in the immune infiltrated stroma within the tumor microenvironment (TME)." (PMID 41249066, 2025). "Most genes considered tumor specific in previous studies (tumor suppressor genes: SOCA3, KLF6, and PTGDS; tumor enhancer genes: SLC38A2, DUSP1, and FGF7) were expressed predominantly in tumor stroma or remission stroma than that in pre-treatment tumors." (PMID 36505794, 2022). "On this basis, CD160, MMP-9, PTGDS, SLC26A8, and TLR5 were selected as indicators of tumor detection." (PMID 36733384, 2022). "Collectively, our results showed the interaction between PTGDS and MYH9 and the anti-tumor effects of MYH9 inhibition in DLBCL." (PMID 34743203, 2022). "Compared to fibroblasts from normal tissues, the top upregulated genes in tumor-derived fibroblasts were CXCL8, CXCL2, CCL2, CXCL3 and CXCL1, and the top downregulated genes were IGFBP5, PTGDS, CCN5, CFD, and RAMP1." (PMID 36357663, 2022). "According to GEO validation results, PTGDS was lowly expressed and SNX10 highly expressed in tumor tissues, which was consistent with the results from immunohistochemistry." (PMID 34116656, 2021). "The results indicated that higher expression of PTGDS was related to higher levels of TIL infiltration, smaller tumours, and earlier pathological stages, which was also consistent with the bioinformatics analysis results." (PMID 32047563, 2020). "Prostaglandin D2 synthase was, however, significantly increased in EP2−/− tumor-bearing mice compared to EP2+/+ tumor-bearing animals." (PMID 26197930, 2015). "The opposite trend was observed with PTGER4, PTGDS, PTGER3, PTGIS, PTGFR, and PTGS1 genes, which showed overexpression in the adjacent non-tumor tissue, followed by downregulation in the tumor." (PMID 26207152, 2015). "BEX1, PTGDS, GRIK2 and WFDC1, also in the top 10 downregulated probesets, have all been identified as downregulated in tumours or as inhibitors of cell proliferation in immortalised cell lines." (PMID 24148222, 2013). "Finally, it is confirmed that the expression of PTGDS in fibroblasts and PTGDR in NK/T cells was downregulated at both the mRNA and protein levels in retrospectively collected paired tumor samples." (PMID 40474982, 2025). "The higher number of seeding locations (≥ 3) showed the downregulation of PTGDS in the tumor (log2FC = − 0.42, adjusted p-value < 0.001) and stromal regions (log2FC = − 0.31, adjusted p-value < 0.001) and ALPL in the tumor region (log2FC = − 0.48, adjusted p-value < 0.001)." (PMID 39135097, 2024). "Another study also showed that MSC-derived EV, prostaglandin D2 synthase (L-PGDS) reduced the levels of stem cell markers (such as Oct4, Nanog, and Sox2) and suppressed the phosphorylation of STAT3, thereby affecting CSC properties and tumor progression." (PMID 39578849, 2024). "REG1A is upregulated in naïve apCAFs, while PTGDS is upregulated in treated endothelial and iCAF cells; neither were observed in tumor cells." (PMID 35995947, 2022). "PTGDS (Prostaglandin D2 Synthase) and HPGD (15-Hydroxyprostaglandin Dehydrogenase) are enriched in the tumor region, while MGST3 (Microsomal Glutathione S-Transferase 3) is depleted in the tumor region in tissue section 1.2." (PMID 32103057, 2020). "Non-tumor components included endothelial cells (expressing VWF, CDH5, ECSCR, SLCO2A1, and MYCT1), pericytes (marked by RGS5, MCAM, and PDGFRB), normal oligodendrocytes (showing PTGDS, MBP, TF, and MOG expression), and TAMs (identified by CD14, AIF1, FCER1G, FCGR3A, TYROBP, and CSF1R)." (PMID 41394801, 2025).
tumor (continued). "In our study, the high expression of PTGDS protein was correlated with worse prognosis in PTCL patients, and targeting PTGDS by gene knockdown and AT56 treatment could suppress tumor growth in vitro and in vivo through regulating cell proliferation, cell cycle, cell apoptosis and invasion." (PMID 39706989, 2025). "Most of the transcriptomic signatures (without subgroup analysis) still show acceptable tumor specificity with the exception of the signature containing PTGDS, CBR3, PTGIR, PTGFR, PTGDR2, and PTGER3 genes in HNSC tumor, which is similar to other tumors (BRCA, CESC, LUAD, SARC, and UCES)." (PMID 35453789, 2022). "The expression of PTGDS, PTGDR and SLCO2A1 also shows a decreasing trend across normal lung, tumor lung, and metastatic brain tissues, as well as in early and advanced stages and at different differentiation levels." (PMID 40474982, 2025).
cancer (20 papers, 2010 to 2025). A tumor composed of atypical neoplastic, often pleomorphic cells that invade other tissues. "Several recent studies have demonstrated that PTGDS has important vascular functions as well as being associated with cancer." (PMID 30393234, 2019). "Eight proteins (C-reactive protein, AGRN, XPOT, LDHA, C1QC, ORM1, ANGPTL4, and prostaglandin D2 synthase [PTGDS]) exhibited a continuously upward or downward trend in three or more cancer types." (PMID 39884577, 2025). "In contrast, PGD2 distinguishes itself within the prostaglandin family through its tumor-suppressive properties, with PTGDS/PGD2 playing important roles in various cancer types and showing tissue specificity in function." (PMID 40474982, 2025). "Among the eRNA–hub gene interaction pairs, 3 eRNAs related to URGs were subsequently selected, and DTX1 had the greatest degree of connection; it was targeted by two eRNAs (PTGDS, TP73-AS1), indicating an association with human cancer that is increasing." (PMID 36681855, 2023). "Increasing evidence suggests that PTGDS also plays a role in cancer processes." (PMID 39355132, 2024). "Here, our study illuminated the cancer-promoting effects of PTGDS in DLBCL." (PMID 34743203, 2022). "Besides, the abnormal glycosylation of PTGDS might influence its intracellular location, half-life, and cancer-promoting role." (PMID 34743203, 2022). "L-PGDS/PTGDS expression is decreased in almost all types of tumors and, thus, can be deemed specific to cancer." (PMID 36765904, 2023). "Other studies have also shown that PTGDS, GREM1, LAMA4, S100A14, PREX2, and GLS2 have potential value in promoting cancer progression and predicting cancer prognosis." (PMID 37306872, 2023). "As a PGD2-production enzyme and lipophilic ligands transporter, the role of PTGDS in cancer has not received much attention." (PMID 34743203, 2022). "Like PTGDS+ fibroblasts, GO terms showed function in ECM deposition and organisation and collagen fibril organisation but also characteristics of endoderm formation and development, which is interesting given that cancer progression shares some gene expression profiles with developmental pathways." (PMID 38165934, 2024).
neurological disorders (6 papers, 2014 to 2023). "Several of these such as NOTCH2, APP, ITM2B and PTGDS have been implicated in neurological disorders." (PMID 36185601, 2022). "Prostaglandin D2 synthase (also called β-trace) itself is a neuroprotective chaperone that inhibits Aβ aggregation, and alterations to its expression may be a biomarker of several neurological disorders." (PMID 36874764, 2022).
infection (5 papers, 2013 to 2025). The state of being infected such as from the introduction of a foreign agent such as serum, vaccine, antigenic substance or organism. "TRBV6-5 and BCL11B are primarily implicated in the immune response post-infection; PTGDS, EGR3, and CXCR5 modulate the host’s inflammatory response." (PMID 39591343, 2024). "Based on these distinct expression patterns, we propose that PTGDS acts as a positive regulator amplifying inflammatory responses, while WISP2 and SLC6A9 may participate in negative feedback mechanisms controlling excessive immune activation during ST infection and HS." (PMID 40563970, 2025).
neurodegenerative disease (3 papers, 2022 to 2024). A disorder of the central nervous system characterized by gradual and progressive loss of neural tissue and neurologic function. "PTGDS is considered a protective factor because it can prevent oxidative stress and apoptosis-related neurodegenerative diseases." (PMID 38087257, 2023).
cardiovascular disease (2 papers, 2011 to 2024). "Despite this similarity, two genes involved in cardiovascular diseases, ADORA1 and PTGDS, were differentially up-regulated in EAT." (PMID 21603615, 2011).
kidney diseases (2 papers, 2015 to 2022). "PTGDS is involved in the advancement of kidney diseases, and has been proposed in the past years as a potential diagnostic marker for renal injury." (PMID 26272683, 2015).
hematological cancers (1 paper, 2022). "However, there is no literature that explores the biological function and mechanism of PTGDS in hematological cancers, especially in DLBCL." (PMID 34743203, 2022).
hematological malignancy (1 paper, 2022). "Taken together, our findings provide evidence for the oncogenic role of PTGDS in DLBCL and further studies will illuminate the role of PTGDS in other hematologic malignancies." (PMID 34743203, 2022). "PTGDS has been involved in various cellular processes including the tumorigenesis of solid tumors, yet its role in carcinogenesis is contradictory and the significance of PTGDS in hematological malignancies is ill-defined." (PMID 34743203, 2022). "Moreover, recent investigations showed that PTGDS acted as modulators of PPARγ, MAPK, and STAT3 pathways, which were associated with the pathogenesis of hematological malignancy." (PMID 34743203, 2022).
inflammation (1 paper, 2023). Aberrant reaction of the microcirculation characterized by movement of fluid and leukocytes from the blood into extravascular tissues. "MiR-511-3p, encoded by the Mrc1/CD206 gene, has also been proven to reduce cockroach allergen-induced lung inflammation and promote M2 macrophage polarization by targeting CCL2 via the RhoA/ROCK axis or prostaglandin D2 synthase (Ptgds)." (PMID 37138859, 2023).
PTGDS also shares sentences with these, for which no sentence is quoted: Obesity (8 papers); diabetes (5); Parkinson disease (4); allergic rhinitis (3); depression (3); diabetic nephropathy (3); ischemic stroke (3); lupus nephritis (3); schizophrenia (3); Cerebral ischemia (2); cervical cancer (2); cervical squamous cell carcinoma (2); chronic kidney disease (2); Crohn disease (2); cryptorchidism (2); Glucose intolerance (2); lung carcinoma (2); metabolic disease (2); papilledema (2); prostate tumors (2); prostatic hyperplasia (2); renal fibrosis (2); serous ovarian carcinoma (2); Stroke (2); tauopathies (2); viral diseases (2); acute coronary syndrome (1); acute kidney injury (1); acute pancreatitis (1); adenomyosis (1).
A further 70 diseases each share a sentence with PTGDS in 1 paper.